CAV1 (caveolin 1)
Diseases named in the same sentence as CAV1 in open-access papers (continued):
Sharing a sentence is not in itself a finding about the gene and the disease.
cancer (continued). "A relationship between Cav-1, cholesterol and invasion in cancer progression indicates that lower cholesterol is beneficial to inhibit the formation of invadopodia." (PMID 31759347, 2019). "Modulation of Cav-1 as a supportive therapy in cancer treatment is clearly recognized and intensively discussed during the recent past." (PMID 31877626, 2019). "Cav-1 has been reported to play a promoting or inhibiting role in cancer progression in many types of tumors, but there are only a few published studies on the role of Cav-1 in gynecological tumor." (PMID 31759347, 2019). "In support of this, caveolin-1 was shown to sequester p85α, which promoted Rac activation, Rab5-dependent endocytosis and migration of cancer cells." (PMID 30650664, 2019). "Overall, the complex role of CAV-1 in cancer explains the divergent results we have observed reflecting patient-to-patient variation in oncogenic events." (PMID 31889941, 2019). "Downregulation of Cav-1 also increased the sensitivity of cancer cells to 5-flourouracil (5-FU), which is also often applied for the treatment of hypertrophic scars." (PMID 31877626, 2019). "Further, Cav1 increases aerobic glycolysis in cancer cells and promotes liver regeneration through hepatic glycolysis." (PMID 31803361, 2019). "CAV-1 is an upstream regulator of the AKT pathway, and the overexpression of caveolin-1 usually induces overactivation of AKT in cancer cells." (PMID 30981205, 2019). "Pseudopodial protrusions are Rho/Rho associated protein kinase (ROCK)-dependent and promoted by phosphorylation of caveolin 1 and activated Src, a family of proto-oncogenic tyrosine kinases which enables cancer cell polarization, cell motility and invasion." (PMID 31198853, 2019). "In turn, downregulation of CAV1 in fibroblasts leads to increased oxidative metabolism in cancer cells, fostering cell resistance." (PMID 30871022, 2019). "In the context of cancer, our findings agree with the proposed role for CAV1 in “metabolic synergy” of solid tumours." (PMID 30209302, 2019). "A number of different mechanisms are summarized, illustrating how CAV1 promotes such traits upon expression in cancer cells (intrinsic mechanisms)." (PMID 31362353, 2019). "There is contradictory evidence of the expression changes of CAV-1 in different cancer tissues, yet clear pivotal role in different oncogenic processes." (PMID 31889941, 2019). "In this work, we focus on the analysis of SMLM images of PC3 cancer cell labeled with antibodies to the membrane protein Cav1." (PMID 31449531, 2019). "A recent series of studies have shown that CAV-1 is usually overexpressed and is responsible for chemoresistance in cancer cells." (PMID 30981205, 2019). "Caveolin-1 (Cav-1), an integral membrane protein, is a principal component of caveolae and has been reported to play a promoting or inhibiting role in cancer progression." (PMID 31759347, 2019). "Cavin-1, a critical structural component of caveolae, was also found to accumulate around the rear of fast-moving cancer cells in 3D matrix and co-localized with caveolin-1." (PMID 31607653, 2019). "How CAV1 can develop such distinct functions in cancer cells represents an important and challenging area of research." (PMID 31362353, 2019). "Whereas the methotrexate-resistant cancer cells demonstrate strong overexpression of Cav-1, which is typical in advanced cancer stages, application of siRNA against Cav-1 effectively decreased this resistance." (PMID 31877626, 2019). "A related mechanism has been uncovered by our group to explain how CAV1 promotes migration and invasion, not only in cancer, but also in dendritic cells." (PMID 31484460, 2019). "With the finding that Cav-1 expression is higher in BM than primary cancer of the SQC type, we provide pivotal insight into the possible role of Cav-1 on EMT via SNAIL." (PMID 31297035, 2019).
cancer (continued). "ECM secretion and remodeling by CAFs have identified the highly expressed integral membrane protein caveolin-1 (Cav1) as facilitating local cancer invasion and metastasis by regulating cell contractility and remodeling via p190RhoGAP." (PMID 31137693, 2019). "Potential anticancer therapy, as chemotherapy shows increased levels of Cav-1 in cancer cells after chemotherapeutic exposure." (PMID 31146391, 2019). "Of these, ALDH1A3, TM4SF1, and PROM1 were identified as cancer stem cell markers and CAV1 was EMT‐related." (PMID 31498560, 2019). "When E-cadherin is still expressed in cancer cells, Cav-1 keeps its anti-proliferative and pro-apoptotic role; whereas, the depletion of E-cadherin resulting in loss of Cav-1 function." (PMID 31759347, 2019). "It has been demonstrated that caveolin-1 not only upregulates CD147 glycosylation but also influences the induction of CD147-dependent MMPs in malignant tumor cells." (PMID 30953513, 2019). "In another study, glutamine was described to increase TIGAR and be needed for CAV1 downregulation in CAFs, decreasing mediators and markers of autophagy in cancer cells." (PMID 30234009, 2018). "Given in vitro and in vivo studies previously showing that caveolin-1 overexpression enhanced cancer invasion and metastasis, we tested the possibility that caveolin-1 is involved in the migration inhibition by neddylation." (PMID 29301501, 2018). "By contrast, accumulating evidence has suggested that CAV1 overexpression correlates with cancer drug resistance, metastasis, the survival of cancer stem cells, and advanced carcinoma." (PMID 30333750, 2018). "A preclinical study shows that Cav-1 expression mediates albumin uptake in cancer cells and directly determines the uptake of nab-paclitaxel in cancer cells." (PMID 30348118, 2018). "The CAV1-mediated anti-cancer effects of ADQ in this study were possibly due to the complex interaction and synergistic/neutralizing effects among the involved compounds." (PMID 30333750, 2018). "Cellular fractionation of CAV1-depleted cancer cells treated with 89Zr-labeled trastuzumab revealed a significant increase (P < 0.001, Student’s t-test) in membrane-associated radioactivity." (PMID 30510281, 2018). "One of the most investigated stromal biomarkers is Caveolin-1, a scaffolding protein shown to have a prognostic significance in numerous cancers, among them primary CRC." (PMID 30602942, 2018). "Accordingly, the Src-caveolin-1 pathway is believed to be critically involved in cancer cell migration." (PMID 29301501, 2018). "Consistent with our findings, previous studies have revealed that multiple active compounds in ADQ exerted anti-cancer effects partly by mediating CAV1 expression." (PMID 30333750, 2018). "NEDD8 seems to inhibit the Src-mediated phosphorylation of caveolin-1 by modifying the structure of caveolin-1 protein, which blocks the migration of cancer cells." (PMID 29301501, 2018). "Cav-1 overexpression enhances uptake and sensitivity to nab-paclitaxel and decreased Cav-1 conferred resistance in cancer cells and in xenograft models." (PMID 30348118, 2018). "It has been shown that leptin and resistin stimulate the Akt signaling in cancer cells, and hyperactivated Akt pathway was associated with increased protein levels of FASN and Cav-1." (PMID 29568521, 2018). "In the same clinical trial, metformin was shown to induce CAV1 expression in CAFs, preventing the metabolic coupling between stromal and cancer cells." (PMID 30234009, 2018). "The results of our study demonstrated that ADQ improved the cancer chemoresponse, and that CAV1 was at least in part responsible for these chemosensitizing effects." (PMID 30333750, 2018). "The ROS secreted by cancer cells can reduce the production of caveolin-1 (Cav-1), an important structural protein that is involved in endocytosis and vesicular transport." (PMID 29534029, 2018). "As expected, Cav1 were down‐regulated in most cancer cell lines, accompanied by the enhancement of Fzd2." (PMID 29502342, 2018).
cancer (continued). "CAV1 expression in cancer was strong in 11.5% (CAV1 average score x ≥ 2), moderate in 14% (score 1 < x < 2), weak in 48% (score 0 < x ≤ 1), and negative in 27% (score x = 0) of the patients." (PMID 29402961, 2018). "The downregulation of Cav-1 in CAFs results in higher ROS levels in cancer cells, which induce oxidative stress in CAFs in a positive feedback loop." (PMID 29967776, 2018). "We suspected the cancer cells which possessed the high expression of caveolin-1 were sensitive to the T-DM1 cytotoxicity being killed during treatment, so the remaining cells showed less caveolin-1 expression." (PMID 29500444, 2018). "In accordance with previous studies, the mean expression of CAV1 was 71% higher in cancer compared to the benign tissue (p < 0.001, Welch’s one-way ANOVA)." (PMID 29402961, 2018). "Cav-1 is suggested to be a potential oxidative stress-related target during oxidative stress-induced cancer initiation and development." (PMID 28546853, 2017). "In contrast, others reported an increased expression of Cav-1 in the more advanced stages of cancers, which still suggest the conflicting impact on cancer progression of Cav-1 protein." (PMID 28828003, 2017). "The perturbations in Cav-1 expression and/or function were, therefore, assumed to play an important part in disease pathogenesis, such as cancer." (PMID 28828003, 2017). "A weak stromal CAV1 expression increases the likelihood of disease recurrence and cancer-related death, and decreases DFS and OS." (PMID 28515480, 2017). "We evaluated the prognostic value of CAV1 expression of both cancer cells and stromal cells in colorectal liver metastases (CRLM) in patients undergoing hepatectomy." (PMID 28515480, 2017). "Drug-sensitive cancer cells display up-regulation of Cav-1 and Cav-2 expression after doxorubicin exposure." (PMID 28498861, 2017). "This is inline with the work from other groups which already demonstrated in other cancer types that Cav1 acts as a pro-survival factor mediating resistance." (PMID 28112237, 2017). "The immunoexpression of CAV1, both membranous and cytoplasmic, was localised to stromal fibroblasts, cancer cells, and endothelial cells of blood vessels." (PMID 28515480, 2017). "Caveolin-1 and filamin A were included in the “Focal Adhesion” and “Proteoglycans in Cancer” pathways." (PMID 28697756, 2017). "From these results, we concluded that Cav‐1 knockdown induces premature senescence in normal and cancer cells." (PMID 28514055, 2017). "Caveolin-1 null cancer cells that contain endogenous ER only show a nuclear pool of the receptor, and ER translocates to the plasma membrane upon introduction of caveolin-1." (PMID 28642789, 2017). "A study using frozen tissues and a monoclonal antibody revealed that Cav-1 is expressed in only a small fraction of intestinal type cancers." (PMID 29141593, 2017). "Alternatively, at later stages of cancer, CAV1 re-expression in lung adenocarcinoma, promotes filopodia formation and increases cell migration, as well as metastatic potential." (PMID 29340103, 2017). "Cancer-related death occurred in 24 of 47 (51%) patients with weak stromal CAV1 expression and in 15 of 62 (24%) patients with strong stromal CAV1 expression (P = 0.005)." (PMID 28515480, 2017). "In the past 20 years, dysregulated Cav1 expression has consistently been detected in various cancers." (PMID 29084770, 2017). "In the present study, we identified that both intestinal and diffuse types of cancers express Cav-1 at highly variable levels." (PMID 29141593, 2017). "It is thus clear that the Janus properties of Cav1 are likely due to cell-specific effects, physiological context, and cancer stage." (PMID 29212030, 2017). "In cancer cells, CAV1 expression promotes cell migration and invasion in vitro and metastasis in vivo." (PMID 29326695, 2017).
cancer (continued). "Herein, we summarize the available evidences about the implications of Cav-1 in the oxidative stress modulation effect of antioxidants and shed novel insights for Cav-1-targeted antioxidant therapy in cancer." (PMID 28546853, 2017). "We also determined the signaling pathways involved in this up-regulation and the functional consequences of CAV1 re-expression in cancer cells were assessed using both in vitro and in vivo approaches." (PMID 29340103, 2017). "In contrast to these observations, the presence of CAV1 reportedly facilitates more aggressive traits in several cancer cell lines, and is related with metastasis, drug resistance, and poor prognosis." (PMID 28099944, 2017). "To further address this issue, we transfected a plasmid containing VSV-tagged AQP4 into three MDA-435 cancer cell lines stably expressing WT Cav1, the dominant negative Y14F form, or one bearing the Y14D phosphomimetic mutation." (PMID 29326556, 2017). "Caveolin-1 (CAV1) is a scaffolding protein that modulates signaling pathways leading to remodeling of the actin cytoskeleton and enhanced migration of cancer cells." (PMID 29326695, 2017). "Cav-1 expression is frequently down-regulated in many human cancers mainly due to promoter hypermethylation whereas its elevation correlates with enhanced progression, multidrug resistance, and metastatic potentials of certain tumors." (PMID 29141593, 2017). "As predicted, a substantial decrease and increase in Cav-1 immunopositivity were observed in 19 (47.5%) and 11 (27.5%) cancer tissues, respectively." (PMID 29141593, 2017). "Forty-seven patients (43%) demonstrated weak stromal CAV1 expression, and 38 patients (35%) demonstrated weak cancer cell CAV1 expression." (PMID 28515480, 2017). "Semi-quantitative DNA-PCR assay revealed that all cancer cell lines and primary tumors we tested have Cav-1 gene levels comparable to those of normal cells." (PMID 29141593, 2017). "We demonstrated that the mechanism of EFHD2 in enhancing EMT occurs partly through inhibition of caveolin-1 (CAV1) for cancer progression." (PMID 29097801, 2017). "Cav-1 is a molecular hub-integrating transduction of multiple cellular molecules which are closely connected with the biological behaviors of cancer cells." (PMID 28546853, 2017). "Several transcription factors are known to regulate the expression of CAV1 during cancer progression." (PMID 29340103, 2017). "Although Cav-1 is secreted by some cancer cells and functions as a paracrine/autocrine factor, Cav-1 levels in endothelial-conditioned media were undetectable." (PMID 26881424, 2016). "MiR-103 has a key role in regulating insulin sensitivity in adipocytes by targeting caveolin-1, and in cancer cell growth and metastasis by repressing different targets, including KLF4 (refs 48, 58, 59)." (PMID 26837267, 2016). "In our study, we found that CAV1 expression exerted a mild effect on the drug sensitivity of in cancer cells." (PMID 26843476, 2016). "Using the PBCre+;Ptenloxp/loxp;PBCav-1+ mouse model we found that Cav-1 induction increased cancer incidence and growth, and ACC1-FASN expression in intact and castrated mice." (PMID 27331874, 2016). "This implies that downregulation of CAV1 in the stromal fibroblast compartment – in parallel with increased aerobic glycolysis – is a mechanism by which HIF1α promotes cancer progression." (PMID 27852311, 2016). "Here we review from a cancer perspective, the findings that CAV1 modulates cell metabolism with a focus on glycolysis, mitochondrial bioenergetics, glutaminolysis, fatty acid metabolism, and autophagy." (PMID 27852311, 2016). "While the potential interaction between IFITM1 and RhoC-GTPase was not directly assessed in our study, it has been reported that Rho-GTPases can interact with caveolin 1 (CAV-1) in cancer cells." (PMID 26897526, 2016). "We found that elevated expression of fatty acid uptake genes, CAV1 and CD36, were consistently associated with a high EMT score across all cancers." (PMID 26725848, 2016).
cancer (continued). "Overall, these results indicate that Cav-1 expression suppresses MnSOD-dependent glycolysis and anoikis that characterize more aggressive cancer phenotypes." (PMID 26543228, 2016). "The function of CAV1 in cancer and specifically in cell migration, invasion and metastasis remains a controversial issue." (PMID 27259249, 2016). "Some studies have shown that CAV1 expression closely correlates with the development of MDR in cancer cells." (PMID 26843476, 2016). "Recent studies reveal that CAV1 is involved in metabolic alterations – a critical strategy adopted by cancer cells to their survival advantage." (PMID 27852311, 2016). "In summary, our current findings indicate that FFLZ is a potential therapeutic or dietary supplemental agent for cancer patients and that it functions via the caveolin-1/Smad7/Smurf2-dependent ubiquitin-mediated degradation of TGFR." (PMID 27830743, 2016). "The results were similar to the treatment with doxorubicin or cisplatin and cells transduced with CAV1 K176R mutant possessed higher resistance to anti-cancer drugs." (PMID 26843476, 2016). "Previous studies reported that the expression level of Cav-1 and MT1-MMP showed to be associated with a poor prognosis and metastasis in several cancers." (PMID 26919102, 2016). "Hormonal regulation of CaV1 channels and the impact of this on their role in the development of particular cancers is a promising area for further investigation." (PMID 27342111, 2016). "Using gene expression profiles, we established a gene-signature (CAV1, CD36, MLXIPL, CPT1C, CYP2E1) that strongly associated with epithelial-mesenchymal program across multiple cancers." (PMID 26725848, 2016). "Taken together, these studies show a context-dependent involvement of CAV1 in autophagy that requires further clarification, especially in cancer types where CAV1 is a key player." (PMID 27852311, 2016). "In conclusion, our results provide critical insight to the mechanisms of CAV1 action during cancer development." (PMID 27259249, 2016). "These genes included ANKLD1, AXL, CAV1/2, LDHB, ETS1, IFI16, PTRF (cavin), KIAA1199 and VIM, which have previously been linked to drug resistance in breast and other cancers." (PMID 26646320, 2016). "It is, however, unclear how variations in Cav-1 expression translate into robust changes in cellular metabolism, particularly in the case of cancer cells." (PMID 26543228, 2016). "To evaluate the effect of the K176R mutant on the interaction between CAV1 and P-glycoprotein, we next examined their protein-protein interaction by immunoprecipitation after treatment with the anti-cancer drug doxorubicin." (PMID 26843476, 2016). "Formation of this complex leads to the formation of lipid-raft Cav-1/Orai1/TRPC1 complex cooperating with SK3 to promote SOCE-dependent cancer cell migration." (PMID 27102434, 2016). "CAV1 is also reported to be involved in diseases such as cancer, cardiovascular disease and diabetes." (PMID 26112043, 2015). "We found that Cav1, a key component involved in β1 integrin-dependent mechanotransduction, was suppressed in most cancer cell lines." (PMID 26189182, 2015). "Clinical findings also suggested that cancer patients with high Cav-1 expression had a worse chemotherapeutic response and worse progression-free survival or overall survival." (PMID 26431273, 2015). "In vitro studies showed the presence of CAV1 in cancer cells undergoing EMT and in fibroblasts undergoing trans-differentiation to CAFs." (PMID 25633184, 2015). "In contrast, when cancer progress to later stage and is treated, expression of Cav-1 would be upregulated to protect cancer cells escape death by speeding aerobic glycolysis, increasing stem cell populations or overexpressing ABC transporters." (PMID 26431273, 2015). "Given the complexity of caveolin-1 cellular and subcellular expression during cancer progression, therapeutic targeting of caveolin-1 is challenging." (PMID 25924234, 2015).